MCM3 (minichromosome maintenance complex component 3)
Diseases named in the same sentence as MCM3 in open-access papers (continued):
Sharing a sentence is not in itself a finding about the gene and the disease.
nasopharyngeal carcinoma (1 paper, 2022). A carcinoma arising from the nasopharyngeal epithelium. "Although there is no study in the literature examining the prognostic effect of MCM3 expression in nasopharyngeal cancer, these results suggest that MCM3 overexpression may be a prognostic factor for nasopharengeal cancer." (PMID 34144903, 2022).
osteoporosis (1 paper, 2023). A condition of reduced bone mass, with decreased cortical thickness and a decrease in the number and size of the trabeculae of cancellous bone (but normal chemical composition), resulting in increased fracture incidence. "Here, we showed that dietary PQQ supplementation could not only promote bone formation of osteoblasts, but also inhibit bone resorption through the activation of stress response and the upregulation of Fbn1 mediated by MCM3‐Keap1‐Nrf2, thus preventing natural aging‐related osteoporosis." (PMID 37365714, 2023).
prostate adenocarcinoma (1 paper, 2021). "IHC staining showed high levels of MCM3 in NEPC cell line tumor xenografts when compared to prostate adenocarcinoma cell line xenografts." (PMID 34172788, 2021).
rectal tumors (1 paper, 2019). "In the in vivo experiments, BTF3-siRNA inhibited the growth of rectal tumors, and in the microarray, we confirmed that BTF3 regulated the cell cycle related gene (MAD2L2, MCM3, and PLK1)." (PMID 31263147, 2019).
renal carcinoma (1 paper, 2021). A carcinoma arising from the epithelium of the renal parenchyma or the renal pelvis. "Phosphorylated MCM3 promotes the proliferation of renal cancer cells and inhibits apoptosis." (PMID 34993142, 2021).
retinoblastoma (1 paper, 2018). A malignant tumor that originates in the nuclear layer of the retina. "Apart from cellular stress response proteins, cell cycle proteins such as CDK1, CDK11, MCM2, MCM3, MCM5, and CCNB1 were also found to be hyperphosphorylated in retinoblastoma, implicating accelerated cell cycle progression." (PMID 29914080, 2018).
sarcoma (1 paper, 2021). A usually aggressive malignant neoplasm of the soft tissue or bone. "Highly expressed MCM3 was also significantly related to poor DFS of sarcoma patients." (PMID 34239894, 2021). "The results showed that high levels of MCM3 and MCM10 mRNA significantly decreased the over survival (OS) (p < 0.05) and disease-free survival (DFS) (p < 0.05) of sarcoma patients." (PMID 34239894, 2021). "The results showed that high expression of MCM2, MCM3 and MCM4 was significantly related to poor OS of sarcoma patients." (PMID 34239894, 2021). "Therefore, MCM2, MCM3, MCM4, and MCM10 were four potential biomarkers for the prognosis of sarcoma and a higher expression indicates worse outcomes." (PMID 34239894, 2021). "So MCM2, MCM3, and MCM4 seemed to be three potential biomarkers for the prognosis of sarcoma." (PMID 34239894, 2021). "Furthermore, we analyzed the prognostic value of MCMs for sarcoma in GEPIA and found that MCM2, MCM3, MCM4, and MCM10 are prognostic biomarkers for human sarcoma." (PMID 34239894, 2021).
serous ovarian cancer (1 paper, 2021). "The serous ovarian cancer dataset indicated that the percentages of DNA alterations of MCMs were 5% (MCM2), 4% (MCM3), 5% (MCM4), 2.6% (MCM5), 1.2% (MCM6), and 5% (MCM7)." (PMID 34178669, 2021).
trisomy 18 (1 paper, 2021). Trisomy 18 is a chromosomal abnormality associated with the presence of an extra chromosome 18 and characterized by growth delay, dolichocephaly, a characteristic facies, limb anomalies and visceral malformations. "Nonetheless, our study reveals important molecules that may be associated with the development of trisomy 18: CCNB2 and MCM3 may be vital." (PMID 34193281, 2021).
tumor (67 papers, 2006 to 2025). "Higher expression of MCM2 and MCM3 was found to correlate with disease recurrence and both proteins were found to be independent prognostic risk factors for tumor free- and overall- survival." (PMID 37197427, 2023). "In addition, HE staining showed that ZMIZ2 overexpression increased nuclear division and relieved inflammatory cell infiltration in tumor tissues, whereas MCM3 knockdown caused evident interstitial fibrosis." (PMID 41502508, 2025). "Notably, multiple studies have demonstrated that elevated MCM3 expression is strongly linked to tumour progression, metastasis, and prognosis." (PMID 38698811, 2024). "MCM3 expression was associated with increased tumour invasion in HCC tissues." (PMID 39628446, 2024). "Our study suggested that MCM3 can be used as a potential prognostic marker for tumours and may be associated with tumour immunity." (PMID 38698811, 2024). "Similarly, MCM3 was generally associated with markers of cuproptosis, anoikis, necroptosis, disulfdptosis and autophagy in most tumours." (PMID 38698811, 2024). "Thus, this study aimed to evaluate the potential association of over-expression of MCM3 with tumor pathology." (PMID 36611359, 2022). "In addition, MCM3 was closely associated with tumour-infiltrating immune cells in most cancers." (PMID 38698811, 2024). "The results of this study prompt us to explore the interaction mechanism between MCM3 and tumor immunity and the potential function of MCM3 in HCC." (PMID 39991578, 2025). "The high expression of MCM3 in HCC patients is associated with T classification, M classification and Tumor stage." (PMID 39991578, 2025). "To further verify the relationship between ZMIZ2 and MCM3 in vivo, we established a mouse xenograft model and monitored tumor growth." (PMID 41502508, 2025). "The growth curve of xenografted TNBC tumors in mice showed that with an increase in the number of days, the tumor volume increased after ZMIZ2 overexpression but remarkably decreased after MCM3 knockdown." (PMID 41502508, 2025). "Minichromosome maintenance 3 (MCM3) protein is upregulated in several cancers, but the biological function, molecular mechanisms and the relationship with tumor immunity of MCM3 in HCC remain poorly understood." (PMID 39991578, 2025). "To compare the expression of MCM3 between tumor and non-tumor tissues, we performed a pan-cancer expression analysis of MCM3 at TIMER 2.0 database." (PMID 39991578, 2025). "qRT-PCR analysis demonstrated that the expressions of MCM3 was significantly downregulated in shMCM3 group tumor samples compared with shNC group." (PMID 39991578, 2025). "Analyzing the clinical characteristics of TNBC revealed a positive MCM3 expression in samples with tumor diameter >2.0 cm (p = 0.003) and higher TNM stage (p < 0.001)." (PMID 41502508, 2025). "The results showed that the expression of MCM3 was significantly increased in tumor tissues (P < 0.001)." (PMID 39991578, 2025). "To further explore the potential mechanism of the ZMIZ2/MCM3 axis in promoting TNBC, we performed RNA sequencing of tumor tissues from a xenograft mouse model in the control, MCM3-sh, and ZMIZ2-OE groups." (PMID 41502508, 2025). "Overall, these data implied that ZMIZ2 contributed to TNBC tumor growth in vivo by regulating MCM3 expression." (PMID 41502508, 2025). "MCM3 knockdown reversed the effect of ZMIZ2 overexpression on TNBC tumor growth both in vitro and in vivo." (PMID 41502508, 2025). "To further explore the potential function of MCM3 in tumor occurrence and development, we evaluated DEG in the TCGA-HCC cohort between the MCM3high and MCM3low groups." (PMID 39991578, 2025). "Subsequently, functional and pathway enrichment analysis was conducted to explore the potential function of MCM3 in tumor occurrence and development." (PMID 39991578, 2025).
tumor (continued). "To further elucidate the regulatory mechanism of the ZMIZ2/MCM3 axis in promoting TNBC, we performed RNA sequencing of tumor tissues from a xenograft mouse model in the control, MCM3-sh, and ZMIZ2-OE groups." (PMID 41502508, 2025). "An example is MCM3, a member of the MCM complex, has been shown to be associated with tumour cell proliferation in multiple cancer types and in functional studies." (PMID 39041188, 2024). "We investigated the relationship between MCM3 and tumour immunity in three aspects, including the TME profile, immune cell infiltration and immune checkpoint factor expression." (PMID 38698811, 2024). "MCM3 expression was positively correlated with immune cell infiltration in most tumours, especially in KIRC, LGG, LIHC, PCPG, PRAD and THCA." (PMID 38698811, 2024). "The results showed that the expression of MCM3 was upregulated in most tumours but significantly lower in KICH tissues than in normal tissues." (PMID 38698811, 2024). "In our previous study, the difference (p < 0.0001) in MCM3 levels between the cells separated by laser capture microdissection (LCM) from SCC tumor tissue and adjusted healthy tissue was 20-fold and 4-fold, respectively." (PMID 37445651, 2023). "Envoplakin (EVPL) was included in the measurement as a ’healthy epidermal tissue marker’ previously determined as a descending protein alongside the ascending protein MCM3 in SCC tumor tissue." (PMID 37445651, 2023). "To systematically elucidate the mechanisms affected by aberrant MCM3 expression and evaluate its clinical significance, we analyzed multi-omics data from the GEO database and validated them in cell lines and tumor samples." (PMID 36133906, 2022). "To systematically investigate the effect of MCM3 dysregulation in MB, we first analyzed tumor-infiltrating cells via three algorithms, including ESTIMATE, CIBERSORT, and XCELL." (PMID 36133906, 2022). "Meanwhile, MCM7 and CDC45, which were involved in this process, were correlated with MCM3 and differentially expressed between normal and tumor tissues." (PMID 36133906, 2022). "The present study systematically analyzed the functions of MCM3 in pediatric MB combined with clinical tumor specimens via multi-mics bioinformatic analysis." (PMID 36133906, 2022). "In tissue microarray, CDC6 and MCM3 protein expression were significant differences by the immunohistochemistry-based H-score between tumor tissues and adjacent tissues, and CDC6 is an independent prognostic factor for GC." (PMID 35537781, 2022). "The expression level of MCM3 is negatively correlated with advanced tumor stage and metastatic status." (PMID 34671420, 2021). "MCM3 expression was significantly related to tumor stage (p < 0.001) and lymph node metastasis (p < 0.001)." (PMID 34671420, 2021). "MCM2, MCM3, MCM6, MCM8, MCM9, and MCM10 groups significantly varied and associated with the tumor stages." (PMID 34490114, 2021). "Evaluation of MCM3 staining showed that its expression was limited to the nucleus of tumor cells, while other cells in the tumor such as lymphocytes and stromal cells were generally negative." (PMID 33398005, 2021). "IHC staining using PCNA as an indicator of tumor cell proliferation revealed the PCNA expression was substantially lower in the sh-MCM3 group compared with the control group." (PMID 32597491, 2020). "Among the most significant genes we identified SKP2, IRF2 and MCM3, all related to tumor progression and metastases." (PMID 31533831, 2019). "MCM3, presented in a variety of human tumors, is involved in tumor proliferation, diagnosis, and prognosis." (PMID 31703725, 2019). "Upregulated BUB1B, CCNB1, CDC7, CDC20, and MCM3 in HCC tumor tissues also contributed to worse DFS in HCC patients (Log rank P = 0.000052, 0.0192, 0.0307, 0.00496, and 0.0284, respectively)." (PMID 30363964, 2018). "BUB1B, CCNB1, CDC7, CDC20, and MCM3 were all overexpressed in HCC patients with neoplasm histologic grade G3-4 compared to those with G1-2 (all P < 0.05)." (PMID 30363964, 2018).
tumor (continued). "BUB1B, CCNB1, CDC7, CDC20, and MCM3 were significantly increased in HCC patients with neoplasm histologic grade G3-4 compared to those with G1-2 (all P < 0.05)." (PMID 30363964, 2018). "The tumor growth curve demonstrated that the knockdown of MCM2 or MCM3 significantly inhibited tumor growth in vivo." (PMID 28460433, 2017). "This condition would justify the conclusion that different proliferating indexes between Ki-67, MCM2, and MCM3 involve an immunoexpression pattern of proliferating tumor cells positive for Ki-67, MCM2, and MCM3." (PMID 26823641, 2015). "MCM3 is overexpressed in multiple malignancies, regarded a more sensitive tumour marker than Ki67, and 90% of mice injected with MCM3 transfected cells developed epithelial tumours within 6 weeks." (PMID 19662092, 2009). "Ki67, Mcm3, and ssDNA expression was confined to tumour cell nuclei, and Bax, Bcl-2, Grp78, and VEGF immunoreactivity to the tumour cell cytoplasm." (PMID 19491899, 2009). "Notably, the A2 tumor area exhibited significant reductions in proteins essential to the DNA replication pathway, including MCM3, MCM4, POLD1, RFC2, and PCNA, all of which are pivotal for maintaining the integrity of DNA replication." (PMID 40076915, 2025). "Our study explored the role of MCM3 in tumor immunity for the first time." (PMID 39991578, 2025). "In vivo study further confirmed that MCM3 downregulation repressed the tumor growth of HCC cells." (PMID 39991578, 2025). "Changes in the expression of these markers were observed in MCM3-silenced tumor tissues." (PMID 41502508, 2025). "Correlation analyses demonstrated that MCM3 expression was closely linked to immune cell infiltration, immune checkpoints, MMR genes, RNA modulator genes, cancer stemness, PCD genes and the TMB in most tumours." (PMID 38698811, 2024). "For example, the MCM protein family (including MCM4, MCM6, and MCM3) plays a key role in DNA replication and cell cycle regulation and may affect tumor immune infiltration by affecting the proliferation and growth of tumor cells." (PMID 39083127, 2024). "Interestingly, genes with oncogenic potential, including CDC42, CDC14B, STK40, BRD3, CPNE1, and MCM3, were downregulated, whereas tumor inhibitors, including CDKN2C, CASP7, and CDKN1B, were upregulated by RBM15 depletion." (PMID 38825643, 2024). "We first investigated the differences in MCM3 mRNA levels between normal and tumour tissues." (PMID 38698811, 2024). "Similarly, MCM3 expression was positively correlated with immune checkpoint factor expression in most tumours, especially in HNSC, KIRC, LIHC, LGG, UVM, KICH, and PRAD." (PMID 38698811, 2024). "Our pan-cancer analysis demonstrated that MCM3, which may have significant prognostic value, was upregulated in 25 tumours, including GBM, LGG, and UCEC." (PMID 38698811, 2024). "Interestingly, KIF20A is a well-known tumor antigen, and MCM3 and MCM5 are critical controllers for regulating cell cycles." (PMID 37884996, 2023). "KI67 and MCM3 mRNA levels were significantly upregulated in Tcam-2 cells cocultured with T cells compared to Tcam-2 cells cultured alone, which indicates that T cells are presumably able to stimulate tumor growth." (PMID 35269507, 2022). "In addition, medium protein expression of MCM3/4/7 was observed in normal tissues, and high protein expression was observed in tumor tissues." (PMID 34404366, 2021). "The expression of MCM2 and MCM3 in EC is correlated with the strong proliferation ability of tumor cells, suggesting that MCM2 and MCM3 may be involved in the proliferation of EC." (PMID 34859821, 2021). "MCM3 expression is upregulated in a variety of malignant tumor cells." (PMID 34671420, 2021). "Multivariate analysis showed that MCM3 expression was independent of tumor size, lymph node status, tumor grade, and age in its association with RFS (p < 0.003) and OS (p < 0.008)." (PMID 33398005, 2021).
tumor (continued). "But these studies only investigate whether MCM3 could be a prognostic factor for various tumors, its role in tumor progression couldn’t be well investigated." (PMID 31208444, 2019). "MCM3 expression could be evaluated in 224/226 (99.1 %) primary tumours and 29/31 (93.5 %) metastases." (PMID 22805320, 2012). "High expression of Chek1, Chek2 and MCM3 has previously been demonstrated to be associated with a poor prognosis in the here studied cohort of tumours, although not independent of other established clinicopathological parameters." (PMID 22284433, 2012). "Therefore, targeting MCM3 may hinder DNA replication in rapidly proliferating tumor cells, including those in TNBC, and MCM3 may be a promising candidate for drug development." (PMID 41502508, 2025). "MCM3 was overexpressed in tumor cells and might be related to malignant transformation." (PMID 36133906, 2022). "Overexpression of DHX9 could rescue MCM2 or MCM3 knockdown-induced tumor inhibition." (PMID 28460433, 2017). "The results showed that MCM2 or MCM3 knockdown could dramatically impede tumor growth in vivo." (PMID 28460433, 2017). "Similarly to MCM2, MCM3 has been studied in different neoplasms." (PMID 26823641, 2015). "However, an assessment of MCM2 and MCM3 expression would be useful to predict tumor behavior." (PMID 26823641, 2015). "Therefore, MCM2 and MCM3 may be used as predictive markers of more aggressive tumor behavior and potentially as important markers to predict the risk of malignant transformation." (PMID 26823641, 2015). "Therefore, it is possible to suggest that high expression of MCM2 and MCM3 may be a more reliable marker of proliferation than is Ki-67 in assessing tumor growth and evaluating the potential for recurrence." (PMID 26823641, 2015). "We confirmed by qRT-PCR and Western blotting that MCM3 mRNA and protein levels were both upregulated in HCC tumor tissues compared with that in paired normal adjacent tissues." (PMID 39991578, 2025). "The results of H&E and IHC showed that the positive rate of MCM3 and PCNA was markedly reduced in shMCM3 group tumor samples compared with shNC group." (PMID 39991578, 2025). "The expression levels of MCM3, BCL2, and N-cadherin increased, whereas those of cyclin A, BAX, and E-cadherin decreased in ZMIZ2-overexpressing tumor tissues." (PMID 41502508, 2025). "Surprisingly, MCM3 was positively correlated with the expression of several immune checkpoint molecules, such as HMGB1, BTN3A2, CD276, and VEGFA, in almost all of the tumours." (PMID 38698811, 2024). "The results showed that MCM3 expression was negatively correlated with the stromal score, immune score, and ESTIMATE score in most tumours, whereas significant positive correlations with these scores were observed in LGG, KIRC and PRAD." (PMID 38698811, 2024). "Additional members of the MCM complex (i.e. MCM2, MCM3, MCM6, and MCM7) were upregulated in all sample groups but basal-like TN tumours." (PMID 36220861, 2022). "Analysis of genes characterizing tumor cell proliferation and cell cycle activity revealed an upregulation of KI67, MCM3, and CDK4 in Tcam-2 cells cocultured with T cells." (PMID 35269507, 2022). "In this study, we systematically assessed the prognostic performance of DNA replication-related genes for predicting tumor recurrence and constructed a novel and robust signature including EREG, KCTD13, MCM3AP, MCM3, POLD2, TERF2, and TP73." (PMID 33748108, 2021). "The expression of four proteins (MCM3, RRM2, NT5DC2, and RNASEH2A) was significantly upregulated in HCC tissues compared to that in non-tumor tissues." (PMID 32213663, 2020). "Our findings revealed that MCM3 promoted radioresistance through activating NF-κB pathway, strengthening the role of MCM subunits in the tumor progression and providing a new target for HCC therapy." (PMID 31208444, 2019). "The tumor volume and weight were smaller in the MCM2 and MCM3 knockdown groups than the scramble group." (PMID 28460433, 2017).